C2orf66 (chromosome 2 open reading frame 66)
Synonyms: UNQ6411; IIDS6411
Gene: Protein-coding gene on chromosome 2 (196,804,417 to 196,809,355, reverse strand). Ensembl gene ENSG00000187944.
Subcellular location: Secreted
Subcellular location (Human Protein Atlas): Nucleoplasm; Cytosol; Predicted to be secreted
Genetic constraint (gnomAD): Loss-of-function variants: 6 observed, 7.3 expected, observed/expected ratio (o/e) 0.82, 90% interval 0.45 to 1.58. That is too few expected variants to judge how well the gene tolerates losing a copy. Missense variants: 107 observed, 118.52 expected, observed/expected ratio (o/e) 0.9, 90% interval 0.77 to 1.06. Synonymous variants: 38 observed, 46.72 expected, observed/expected ratio (o/e) 0.81, 90% interval 0.63 to 1.07.
Homologues: Orthologues: chimpanzee C2BH2orf66 (99% identical), macaque C2H2orf66 (95% identical), rabbit C2orf66 (79% identical), dog C2orf66 (78% identical), pig C2orf66 (74% identical), mouse Gm34066 (72% identical), rat C9h2orf66 (69% identical), zebrafish pgap1 (30% identical), Drosophila melanogaster PGAP1 (25% identical), Caenorhabditis elegans pgap-1 (16% identical). Paralogues in human: PGAP1 (27% identical).